ADAM17 (ADAM metallopeptidase domain 17)
Diseases named in the same sentence as ADAM17 in open-access papers (continued):
Sharing a sentence is not in itself a finding about the gene and the disease.
infection (continued). "Further investigations in models of sterile infection revealed a time-dependent effect of ADAM17 in neutrophil recruitment, which is dependent on L-selectin shedding at early time points." (PMID 33392273, 2020). "First, ADAM17 acts after virus primary binding/release, because infection is almost blocked in ADAM17-depleted recipient cells, receiving viral particles from control donor cells." (PMID 31107240, 2019). "In this study, we identify the ADAM17 protease as an important host cell factor in infections by oncogenic human papillomaviruses." (PMID 31107240, 2019). "As expected, ADAM17 depletion in donor cells strongly diminished their infection, but also halved the infection of non-ADAM17-depleted recipient cells." (PMID 31107240, 2019). "Supplying the medium with EGF did not only abolish diminished ERK phosphorylation after ADAM17 depletion, but as well restored infection in ADAM17-depleted cells." (PMID 31107240, 2019). "Altogether, this indicates that ADAM17 is important for the infection with oncogenic human papillomaviruses." (PMID 31107240, 2019). "We find less AREG and TGF-α in the supernatant of ADAM17-depleted cells, corroborated by a reduction of the infection rate after treatment with AREG and TGF-α neutralizing antibodies." (PMID 31107240, 2019). "ADAM17 was also required for the infection by two other highly oncogenic HPV types, HPV18 and HPV31." (PMID 31107240, 2019). "Upper panels, immunoblots for ADAM17 illustrating the efficiency of ADAM17 depletion (β-actin served as a loading control), whereas lower panels display the infection rate." (PMID 31107240, 2019). "Yet, EPCR shedding induced by N. meningitidis 4 hours after infection was identical in ADAM17-siRNA or control-siRNA transfected cells." (PMID 29630665, 2018). "ADAM17 is regarded as a first line of defense against injury and infection, by releasing tumor necrosis factor α (TNFα) to promote inflammation and epidermal growth factor (EGF) receptor ligands to maintain epidermal barrier function." (PMID 27256961, 2017). "Here, we use mice with a T-cell restricted ADAM17-deficiency (Adam17fl/fl×CD4cre+ mice) to investigate the role of ADAM17 in T cells under homeostatic conditions and following infection of mice with L. monocytogenes." (PMID 28877252, 2017). "Neutrophil recruitment at the site of infection was again found to be greatly increased in conditional ADAM17 knockout mice compared to control mice, and this likely accounted for the enhanced clearance of bacteria." (PMID 28487846, 2017). "This study investigated the plasma levels of ADAM17 and Ang2 in Tanzanian children admitted to the hospital with UM, SM, or with other infections, and the potential correlations between ADAM17 or Ang2 and PfEMP1 subtype expression." (PMID 27784899, 2016). "Transcript levels for tumor necrosis factor-α converting enzyme (TACE)/α-disintegrin and metalloproteinase (ADAM)-17 increased during days 4 to 6 after infection." (PMID 17725815, 2007). "We noted an increase in TNF-α converting enzyme/α-disintegrin and metalloproteinase (ADAM)-17 at days 4 to 6 after infection, peaking at an average 3.1-fold increase above baseline at day 5 after infection." (PMID 17725815, 2007). "The cellular ADAM17 levels did not significantly affect achievable titers, supporting the conclusion that either small amounts of ADAM17 are likely sufficient to mediate infection or that ADAM17 cell surface levels don’t directly correlate with the total cellular ADAM17 pool." (PMID 39459898, 2024). "Mature ADAM17 levels were reduced upon infection with a cytopathic pestivirus bovis (bovine viral diarrhea virus, cpBVDV), pestivirus suis (classical swine fever virus, CSFV) or pestivirus giraffae (strain giraffe), but not negatively affected by pestivirus L (Linda virus, LindaV)." (PMID 39459898, 2024). "CRIB cells, which are resistant to infection with BVDV do not express functional full-length ADAM17 mRNA and have two defective alleles of the protein." (PMID 38041163, 2023).
infection (continued). "Therefore, we examined the impact of ADAM17 activity on transepithelial migration of monocytic cells (THP-1 cells) during infection with P. aeruginosa." (PMID 35892600, 2022). "Therefore, we used an ADAM10 inhibitor (GI254023X, a competive inhibitor with 100-fold higher specificity for ADAM10 versus ADAM17) during infection to increase peripheral resistance and vessel stiffness simultaneously." (PMID 35446924, 2022). "In A549 cells, the Gram-negative bacterium Pseudomonas aeruginosa (P. aeruginosa) induced protein expression and maturation of ADAM17, shown by a stronger expression (densitometric analysis) of the 100 kDa mature form and the 130 kDa pro-form of ADAM17 after 4 h of infection." (PMID 35892600, 2022). "In the present study, we could show a pathogen-dependent regulation of ADAM17 in alveolar epithelial cells during infection with P. aeruginosa and S. pneumoniae." (PMID 35892600, 2022). "ADAM-17 is considered to be the key molecule that may explain uncontrolled IL-6 trans-signaling and increased proinflammatory responses during infection." (PMID 33628091, 2021). "Upon infection, soluble ACE2 enzymatic activity in nasopharyngeal swabs may increase in some patients, probably due to the infection itself and/or the activity of sheddase ADAM17 and TMPRSS2." (PMID 34578296, 2021). "Therefore, ADAM-17 should be thought of as a potential target molecule for novel antiviral drug discovery that can regulate host reactivity to infection and, in turn, limit or prevent fatal outcomes." (PMID 33628091, 2021). "On the other hand, the increased expression of IL-1β, as a consequence of the inflammatory process induced by SARS-CoV-2 infection, may also contribute to the over-activation of ADAM17 in the early stage of the infection." (PMID 33117379, 2020). "Furthermore, down-regulation of ACE2 severely worsened the outcome in SARS-CoV infection, and pharmacological inhibition and gene silencing of ADAM17 showed a markedly decrease of infection in in vitro and in vivo models." (PMID 33392273, 2020). "The mRNA expression of ADAM17 was gradually increased at the periods of infection." (PMID 32269560, 2020). "The sACE2, produced by ADAM-17, will both bind to viral particles blocking their entry into the cells, and thus protecting the organism from infection, while also cleaving ANG II, thus controlling both the neutrophilic infiltration and the inflammatory response." (PMID 33519802, 2020). "Under all conditions ADAM17 depletion consistently and strongly decreased infection." (PMID 31107240, 2019). "Moreover, GF treatment increased infection rates in the absence as well as in the presence of ADAM17 in a concentration-dependent manner." (PMID 31107240, 2019). "Through real-time PCR, we have shown that ADAM17 was the key player in mediating EGFR activation, by the demonstration that ADAM17 inhibitor TAPI-1 treatment significantly suppressed the infection-induced transactivation of EGFR by preventing the proteolysis and secretion of HB-EGF." (PMID 30687645, 2018). "We detected similar listeria titers in spleen and liver of Adam17fl/fl×CD4cre+ and Adam17fl/fl×CD4cre- mice at day 5 of primary and day 2 of secondary infection indicating that ADAM17-deficient T cells were not impaired in controlling L. monocytogenes." (PMID 28877252, 2017). "We lost 3 Adam17fl/fl×CD4cre- mice (3.1%) and 8 Adam17fl/fl×CD4cre+ mice (8.2%) due to infection, which further confirms that ADAM17-deficiency does not substantially weakens the T-cell response to L. monocytogenes." (PMID 28877252, 2017). "The increased ADAM17 concentrations in the plasma may be part of a general inflammatory response to infection and seemed to be unspecific." (PMID 27784899, 2016).
infection (continued). "Despite this, there is little evidence about the association of ADAM17 with TB, a prototype infectious disease where immune regulation is pivotal in maintaining infection control at the lowest tissue-damage cost during LTB and displaying intense necrosis of granuloma in ATB progressors." (PMID 38881671, 2024). "Together, both studies favor the assumption that ADAM17 takes a role during infection by modulating the production of inflammatory molecules, mainly TNF, which is required for protective immunity during LTB but could be detrimental when it is produced in excess, as in septic shock." (PMID 38881671, 2024). "In cell-based assays, we could show that the protein expression, maturation, and activation of ADAM17 is upregulated upon infection of lung epithelial cells with Pseudomonas aeruginosa and Exotoxin A (ExoA), without any impact of infection by Streptococcus pneumoniae." (PMID 35892600, 2022). "We conclude that different proteases, including TMPRSS2, ADAM10, ADAM17, and potentially others, may prime S2 and, thus, facilitate: (i) infection through the fusion of the SARS‐CoV‐2 virus with host cells, or (ii) syncytia formation of S‐expressing SARS‐CoV‐2‐infected cells with host cells." (PMID 35527514, 2022). "Therefore, we used an alternative approach and tested whether recombinant sACE2—the ADAM17 shedding product of ACE2—affects A549‐ACE2 infection with the spike pseudoparticles (VSV‐S)." (PMID 35527514, 2022). "Second, we did not clarify whether abnormal ADAM17 activation is directly involved in patient susceptibility to infection, and additional clinical research is needed to address this issue." (PMID 32180373, 2020). "Whether treatment with an ADAM17 inhibitor would also improve bacterial uptake by either microglial cells or potentially also by peripheral phagocytes and thereby improved antibacterial defence needs to be further studied in murine models of infection." (PMID 32825187, 2020). "However, there are several possible explanations for the lower infection rate of non-ADAM17-depleted recipient cells: recipients have received (i) less virus particles, (ii) the same amount but less infectious particles, or (iii) less bioactive molecules required for signaling pathway activation." (PMID 31107240, 2019). "However, while our data raise the possibility that ADAM17 may mediate part of the increased susceptibility to infection in patients with AP and AAH, they cannot be taken to imply a role for ADAM17 in the primary pathogenesis of these conditions." (PMID 31507587, 2019). "Therefore, the involvement of ADAM17 in the release of soluble bioactive compounds, as for example growth factors, which activate specific signaling pathways for infection and can also decorate the virus, might explain these findings." (PMID 31107240, 2019). "We used the rescued strain rSczy3 to infect CEKs and performed qRT-PCR to evaluate the relative expression levels of CTSL, CTSB, Abl1, Abl2, IFITM3, ADAM17, TMPRSS2, NRP1, and CD74 at 12 and 24 h post-infection." (PMID 37376546, 2023). "As notch signaling positively regulates protease furin, protease ADAM Metallopeptidase Domain 17 (ADAM17), and angiotensin-converting enzyme 2 (ACE2) to promote SCV2 entry and infection to the host cells." (PMID 37504520, 2023). "When ADAM17 was provided in trans in CRIB-1 cells, their resistance to infection with a diverse array of pestivirus (BVDV-1, HoBiPeV, CSFV, LindaV) was nearly completely reverted." (PMID 38041163, 2023). "Once ADAM17 was provided in trans in CRIB-1 cells, their resistance to infection with a diverse array of pestiviuses (BVDV-1, HoBiPeV, CSFV, LindaV) was nearly completely reverted." (PMID 35215974, 2022). "ADAM17, which facilitated SARS‐CoV‐2 cell infection, is known to cleave the S receptor ACE2, which is a single‐span transmembrane protein." (PMID 35527514, 2022).
infection (continued). "MDBK cells, CRIB-1 cells or the respective cells expressing ADAM17 or SH3BGRL were infected with an MOI of 0.001 and analyzed 72 h post infection to determine the amount of fluorophore positive cells in a flow cytometer." (PMID 35215974, 2022). "Blocking ADAM17 and CD62L shedding in other innate leukocytes, such as neutrophils, during sterile inflammation and infection also enhanced their migration to tissue locations." (PMID 34367174, 2021). "Of note, activation of ADAM17/TACE metalloprotease was induced by SARS-CoV and necessary for efficient infection (and TNF-α secretion)." (PMID 32708755, 2020). "ADAM10 and ADAM17 together with ADAM8 and ADAM9 seem to be the most relevant ADAM proteases in infection; however, some studies point toward an additional influence of ADAM12, ADAM15, and ADAM33." (PMID 33392273, 2020). "Our results imply that a low CD9 level supports ADAM17-mediated ERK activation and consequently HPV16 entry and infection." (PMID 32385608, 2020). "Infection significantly increased the expression of ACE2, TMPRSS2, ADAM17, TGFB1, CTGF, VEGFA and FN1 but resulted in trends towards decreases in TIMP3 (p = 0.083) and AGF (p = 0.086) in A549 cells compared to control cells." (PMID 32664949, 2020). "Hp induced the expression of ADAM17 both at the mRNA and protein levels in THP-1-derived macrophages, while this induction was significantly reduced during infection with H. pylori in the presence of L. gas." (PMID 31636639, 2019). "Adding ADAM17 cleavage products such as AREG, TGF-α, and HB-EGF to the supernatant of serum-starved or ADAM17-depleted cells increases ERK1/2 phosphorylation and infection." (PMID 31107240, 2019). "For example, EGF increases the infection rate of ADAM17-depleted cells, EGF increases the proximity between L1 and CD151 after ADAM17 knockdown, and ADAM17 knockdown diminishes the overlap between L1 and EGFR." (PMID 31107240, 2019). "Our data suggest ADAM17-mediated release of GFs such as AREG, TGF-α or HB-EGF, known activators of ERK signaling as an important step in infection with oncogenic papillomaviruses." (PMID 31107240, 2019). "EGFR is a proviral factor in HPV16 entry (A) and soluble EGF relieves the effect of ADAM17 depletion on the phosphorylation status of ERK1/2 (B, C), HPV16 PsVs infection rate (D) and HPV16-CD151 proximity (E, F)." (PMID 31107240, 2019). "To further verify the involvement of ADAM17, we treated the cells with TAPI-1, a specific inhibitor of ADAM17, prior to PCN033 infection, and found that the time-dependent phosphorylation of EGFR induced by PCN033 was completely blocked by TAPI-1." (PMID 30687645, 2018). "To further support this result, we studied the membranous expression of EPCR after 4 hours of infection with a WT strain in the presence of 25 μM of TAPI-0, a drug known to inhibit all metalloproteases of the ADAM family, including ADAM17." (PMID 29630665, 2018). "We therefore analyzed the ability of the specific TACE/ADAM17 inhibitor, TNF-α protease inhibitor–1 (TAPI-1), to block TNFR1 release in response to infection with the carriage isolates." (PMID 22144896, 2011). "We found that transcript levels for ADAM-17 increased on days 4 to 6 after infection, peaking at day 5 after infection, which is consistent with a role for ADAM-17 in shedding of GP1,2Δ during in vivo primate infection." (PMID 17725815, 2007). "Although previous studies have identified certain polymorphisms in the ACE2, ADAM17, FURIN, IFITM3, and VDR genes associated with infection susceptibility to SARS-CoV-2, our findings did not reveal any such associations (data not shown)." (PMID 40296872, 2025). "As early as 24 h post infection, infected cells became detectable in immunofluorescence staining across all cultures, irrespective of ADAM17 expression." (PMID 39772144, 2024). "Infection with DNA and RNA viruses (influenza A, RSV) upregulates Rhbdf2 and ADAM17 genes." (PMID 36851081, 2023).
infection (continued). "The intracellular retention of ADAM17 mediated by UL148 and UL148D may be expected to affect the expression of additional viral and cellular proteins during infection." (PMID 37561786, 2023). "For example, HIV is known to alter the composition and function of EVs, leading to the secretion of infection-promoting host proteins such as virus receptors CCR5 and CXCR4, metalloprotease ADAM17 and other proinflammatory factors, and host restrictive factors such as APOBEC3G and TRIM5α." (PMID 37396389, 2023). "High levels of ADAM17 and increased activity in placental villous tissue may indicate that ACE2 shedding is an important response to infection in the placenta and upregulation of ADAM17 may be protective against SARS-CoV-2 related placental outcomes." (PMID 36952548, 2023). "It has been previously reported that ADAM17 and TMRPSS2 compete for substrates, including the SARS-CoV-2 receptor ACE2, and both metalloproteases and serine proteases are co-expressed in several infection-competent cells." (PMID 36298651, 2022). "It is therefore possible that MT1-MMP and ADAM17 may work synergistically in the regulation of ACE2 shedding and hence the infection of SARS-CoV-2." (PMID 36564389, 2022). "A pathway involving NOTCH signaling, furin, ADAM17, and ACE2 may be capable of increasing SARS-CoV-2 viral entry and infection." (PMID 35992174, 2022). "Double knock‐out (ADAM10/17 KO) cells lacking both ADAM10 and ADAM17 showed the strongest reduction of infection similar to BB94‐treated NTC cells, and this double knock‐out effect was not significantly further reduced with additional BB94 treatment." (PMID 35527514, 2022). "Infection with P. aeruginosa or stimulation with ExoA as representative of its major virulence toxins increased ADAM17 protein expression and activity, whereas no changes upon infection with S. pneumoniae were observed." (PMID 35892600, 2022). "Due to its diverse array of substrates, it is no surprise that ADAM17 plays an important role in controlling infection." (PMID 35215094, 2022). "On the other hand, neither protein expression nor maturation of ADAM17 was changed upon infection with the Gram-positive bacterium Streptococcus pneumoniae (S. pneumoniae)." (PMID 35892600, 2022). "Both S and ACE2 are also required for lung cell infection, raising the possibility that syncytia formation may also depend on ADAM10 and/or ADAM17 and may be blocked by metalloprotease inhibitors." (PMID 35527514, 2022). "In infection experiments, we demonstrated hDsg2 shedding from H. pylori-colonized MKN28 and NCI-N87 cells independently of pathogen-induced matrix-metalloproteases or ADAM10 and ADAM17." (PMID 34742300, 2021). "Overexpression of ADAM17 inhibited PRRSV infection by regulating CD163 expression, whereas the reduction of ADAM17 expression by siRNA led to upregulation of CD163, which further increased infection with PRRSV." (PMID 33916997, 2021). "Furthermore, L-selectin was shown to support the preferential infection of central memory CD4+ T cells, with L-selectin shedding by ADAM17 being required for viral release." (PMID 33392273, 2020). "Therefore, the TMPRSS2/ADAM-17 balance would be shifted towards TMPRSS2 activation, thus favoring infection by the virus." (PMID 33519802, 2020). "Additionally, when infection by SARS-CoV-2 occurs, the virus is internalized and this triggers the activation of ADAM metallopeptidase domain 17 (ADAM17)." (PMID 32825068, 2020). "In addition, ADAM17 can also be activated in response to pathogen infection through Toll-like receptors and may involve the translocation of phosphatidylserine (PtdSer) to the outer cell membrane leaflet, a crucial step for ADAM17 to exert its “sheddase” activity." (PMID 33117379, 2020). "Further, ADAM17 mediated shedding of the Chlamydia trachomatis receptor glucose regulated protein 96 (Gp96) protected against re-infection, whereas reduction of TNFRI expression on the cell surface facilitated the infection." (PMID 33392273, 2020).